ANGPTL2 (angiopoietin like 2)
Diseases named in the same sentence as ANGPTL2 in open-access papers (continued):
Sharing a sentence is not in itself a finding about the gene and the disease.
leukemia (9 papers, 2019 to 2024). A malignant (clonal) hematologic disorder, involving hematopoietic stem cells and characterized by the presence of primitive or atypical myeloid or lymphoid cells in the bone marrow and the blood. "More efforts are required to fully illustrate the underlying regulatory networks of ANGPTL2 in normal hematopoiesis and hematomalignancies to provide new insights for the treatment of leukemia." (PMID 37751067, 2024). "Endothelial cells (ECs)-derived small extracellular vesicles contained a high level of ANGPTL2, which accelerated leukemia progression via binding to the LILRB2 receptor." (PMID 38546813, 2024). "In particular, our group recently showed that EC-derived ANGPLT2 is required for the self-renewal ability of HSCs, suggesting that ANGPTL2 has different effects on different cell types, such as HSCs or leukemia cells." (PMID 37751067, 2024). "We showed that LILRB2 was the receptor for ANGPTL2 to sustain the stemness of HSCs and leukemia stem cells." (PMID 36855057, 2023). "Small extracellular vesicles that contains ANGPTL2 derived from vascular endothelial cells has been reported to promote the progression of leukemia." (PMID 37426414, 2023). "SEVs derived from endothelial cells contained high levels of Angiopoietin-like protein 2 (ANGPTL2) protein, which binds to the leukocyte immunoglobulin-like receptor B2 (LILRB2 receptor) and accelerates leukemia progression." (PMID 37842232, 2023). "Moreover, this subset also shares leukemia and pro‐B gene expression signatures as well as high levels of the ETV6 target genes (BIRC7, WBP1L, CLIC5, ANGPTL2) with the ER subtype, indicating that these B‐other cases are the recently identified ER‐like subtype." (PMID 33987955, 2021).
metabolic syndrome (9 papers, 2013 to 2023). A cluster of metabolic risk factors for CARDIOVASCULAR DISEASES and TYPE 2 DIABETES MELLITUS. "Angptl2 plays multiple important roles in metabolic syndrome, inflammatory carcinogenesis, and tumor metastasis." (PMID 34638684, 2021). "Moreover, Angptl1 and Angptl2 have been reported to be involved in metabolic syndrome in human and rodents." (PMID 33910546, 2021). "In this sense, we have found similar results in HS patients, although ANGPTL2 was related to the severity of HS independently of BMI, the presence of metabolic syndrome, and serum levels of hs-CRP, indicating that it could be a biomarker of the HS severity by itself." (PMID 37189824, 2023). "Moreover, ANGPTL2 was related to HS severity measured by the IHS4, and this association is independent of age, BMI, metabolic syndrome, serum hs-CRP levels, and IR." (PMID 37189824, 2023).
coronary artery disease (8 papers, 2013 to 2024). "Oxidative stress-induced premature senescence observed in endothelial cells from active smokers with severe coronary artery disease was associated with higher (4-folds) levels of ANGPTL2 mRNA." (PMID 29138671, 2017). "Cellular senescence is associated with aging and various chronic diseases, and we originally isolated ANGPTL2 from senescent vascular endothelial cells of patients with severe coronary artery disease." (PMID 29138671, 2017). "ANGPTL2 is a circulating pro-inflammatory protein that increases with age and prematurely in patients with coronary artery diseases; integrating the methylation pattern of the promoter may help differentiate age- vs. disease-related change in its expression." (PMID 27101308, 2016). "Methylation of different CpGs in ANGPTL2 gene may prove to be a reliable biomarker of coronary disease." (PMID 27101308, 2016). "Importantly, our data suggest that methylation of different CpGs in ANGPTL2 may prove to be a reliable biomarker of coronary disease." (PMID 27101308, 2016). "Our group has previously demonstrated that patients with chronic documented coronary artery disease exhibit greater signs of inflammation through slightly higher circulating ANGPTL2 (3.35 ± 0.67 ng/mL for post-ACS versus 5.74 ± 0.75 ng/mL for CAD)." (PMID 27101308, 2016). "Long-term follow-up study has shown that higher serum ANGPTL2 levels increase the frequency of CVD, including coronary heart disease and stroke in the Japanese population." (PMID 31743976, 2019).
ovarian carcinoma (8 papers, 2015 to 2022). A malignant neoplasm originating from the surface ovarian epithelium. "Conversely, ANGPTL2 was found to suppress the growth of ovarian cancer cell and loss of its function is implicated in carcinogenesis of ovarian cancer." (PMID 29389861, 2018). "In ovarian cancer, ANGPTL2 can even reduce peritoneal metastasis of tumor cells by inhibiting anoikis resistance." (PMID 36291283, 2022). "For example, hypermethylation of CpGs located in ANGPTL2 gene have been reported in various ovarian cancer cell lines, where ANGPTL2 is silenced and in bone marrow samples from patients suffering from primary myelodysplastic syndrome." (PMID 27101308, 2016).
prostate carcinoma (8 papers, 2015 to 2023). A carcinoma that arises from epithelial cells of the prostate gland. "Here, we found a positive association between ANGPTL2 expression and immune-related risk score in prostate cancer." (PMID 33197890, 2020). "Prostate cancer is most likely to develop bone metastases, and prostate cancer-derived miR-378a-3p-containing EVs promote osteolysis by activating the Dyrk1a/Nfatc1/Angptl2 axis in bone marrow macrophages during tumor bone metastasis." (PMID 38037077, 2023). "Exosomal miR-378a-3p promoted prostate cancer progression and osteolysis by targeting Dyrk1a/Nfatc1 pathway in bone marrow macrophages leading to increased secretion of angiopoietin like 2 (Angptl2) into the bone microenvironment." (PMID 35994202, 2022). "In this study, we constructed a model using a Cox proportional hazards model based on the expression of eight immune-related genes that were associated with prognosis in prostate cancer: EDNRB, ANGPTL2, TNFSF15, TNFRSF10D, EDN2, BMP2, NLRP14, and PLK1." (PMID 33197890, 2020). "ANGPTL2 downregulation by siRNA has been shown to inhibit cell growth, migration, and invasion of prostate cancer cells (LNCaP)." (PMID 31384179, 2019). "In prostate cancer, androgen deprivation increases ANGPTL2 cancer tissue levels leading in turn to androgen-indipendent and malignant behavior of prostatic cancer cells through an autocrine and/or paracrine manner via integrin α5β1 receptor." (PMID 29389861, 2018). "The downregulation of ANGPTL2 expression by siRNA inhibits cell growth, migration and invasion of LNCaP cells and androgen-independent prostate cancer cell line model LNCaP/AI." (PMID 25370833, 2015). "Our findings suggest that blocking ANGPTL2 is useful as a therapeutic strategy against prostate cancer progression." (PMID 25370833, 2015). "By contrast, decreasing ANGPTL2 levels in human prostate cancer cells attenuated cell growth and malignant behavior." (PMID 25370833, 2015). "The expression of mRNA and protein of ANGPTL2 was confirmed in the other prostate cancer cell lines (PC-3, DU145 and 22Rv1) using western blot analysis and immunohistochemical staining." (PMID 25370833, 2015). "Immunohistochemical staining revealed that ANGPTL2 was expressed at higher levels in human prostate cancer tissues after androgen ablation therapy than in human prostate cancer tissues without androgen ablation therapy." (PMID 25370833, 2015). "Targeting ANGPTL2 pathway may be then a novel promising therapeutic approach for prostate cancer, especially in androgen-independent state." (PMID 29389861, 2018). "Therefore, the aims of this study were i) to define the biological effects of ANGPTL2 in prostate cancer cells, and ii) to examine the role of ANGPTL2 as a novel therapeutic target for prostate cancer." (PMID 25370833, 2015). "Targeting ANGPTL2 may therefore be an efficacious therapeutic modality for prostate cancer, especially androgen-independent prostate cancer." (PMID 25370833, 2015). "Human prostate cancer cell lines predominantly expressed ANGPTL2 among the members." (PMID 25370833, 2015). "Thus, ANGPTL2 is an effective growth-promoting factor and an important determinant of the potential malignancy of androgen-independent prostate cancer cells." (PMID 25370833, 2015). "ANGPTL2 may be important in the acquisition of androgen independency and tumor progression of prostate cancer in an autocrine and/or paracrine manner via the integrin α5β1 receptor." (PMID 25370833, 2015). "MiR-378a-3p from prostate-cancer-cell-derived EVs promoted osteolysis through activation of the Dyrk1a/Nfatc1/Angptl2 axis in bone marrow macrophages, which played an important role in prostate cancer bone metastasis and could be a potential predictor of metastatic prostate cancer." (PMID 37046819, 2023). "In addition, ANGPTL2 may promote acquisition of androgen independence and tumor progression in prostate cancer by exerting autocrine and/or paracrine effects via the integrin α5β1 receptor." (PMID 33197890, 2020).
prostate carcinoma (continued). "Moreover, the authors showed that ANGPTL2 is upregulated in human prostate cancer tissues after neoadjuvant hormonal therapy and this result suggests its clinical relevance in the hormone refractory mechanisms of prostate cancer." (PMID 29389861, 2018). "Targeting ANGPTL2 may therefore be an efficacious therapeutic modality for prostate cancer." (PMID 25370833, 2015). "In conclusion, ANGPTL2, which is upregulated in androgen-independent prostate cancer cells and human prostate cancer tissue after androgen ablation therapy, may be important in androgen-independent prostate cancer progression in an autocrine and/or paracrine manner via the integrin α5β1 receptor." (PMID 25370833, 2015). "Prostate-cancer-cell-derived EVs loaded with miR-378a-3p accelerated osteolysis by targeting the Dyrk1a/Nfatc1 axis to upregulate ANGPTL2 expression and secretion, thereby promoting PMN formation and enhancing prostate cancer metastasis." (PMID 37046819, 2023). "The role of ANGPTL2 in prostate cancer development has not been reported in connection with androgen independency and malignant behavior." (PMID 25370833, 2015). "However, we did not observe a tumor suppressor function for ANGPTL2 in human prostate cancer cells." (PMID 25370833, 2015).
acute coronary syndrome (6 papers, 2016 to 2022). Signs and symptoms related to acute ischemia of the myocardium secondary to coronary artery disease. "In leukocytes from acute coronary syndrome patients compared to healthy controls, a methylation study of a pro-inflammatory protein-encoding gene ANGPTL2 revealed a decreased promoter methylation associated with higher ANGPTL2." (PMID 36551003, 2022). "Serum ANGPTL2 is also a new candidate biomarker for risk stratification of acute coronary syndrome." (PMID 33256685, 2020). "Thorin-Trescases and colleagues reported in patients with acute coronary syndrome after 3 months of physical training, which the plasma levels of ANGPTL2 decreased to 26%, while body mass, lean and fat mass, waist circumference, and BMI were not affected by the exercise training program." (PMID 29932432, 2018). "To test this hypothesis we investigated the changes in promoter methylation of ANGPTL2 gene in leukocytes from patients suffering from post-acute coronary syndrome (ACS)." (PMID 27101308, 2016). "In addition, we showed that in patients with acute coronary syndrome, the reduction of ANGPTL2 levels induced by the training program correlated with endothelial function measured at baseline: better initial endothelial function correlated with lower ANGPTL2 levels reached after exercise." (PMID 29138671, 2017).
chronic kidney disease (6 papers, 2016 to 2021). Impairment of the renal function secondary to chronic kidney damage persisting for three or more months. "Few years later, in a general Japanese population, elevated circulating ANGPTL2 levels mainly related to albuminuria were found to be an independent predictor of chronic kidney disease prevalence." (PMID 29138671, 2017). "We also previously reported that ANGPTL2 activates ERK through integrin α5β1 in chronic kidney disease." (PMID 28043948, 2017). "We recently reported that in patients with severe chronic kidney disease (stage 5), kidney transplantation dramatically reduced serum ANGPTL2 levels, raising the possibility that the diseased kidney was a source of ANGPTL2." (PMID 29138671, 2017). "Thus, in combination with inflammation, renal fibrosis induced by ANGPTL2 contributes to chronic kidney disease." (PMID 29138671, 2017). "In accordance with this hypothesis, we recently reported that in patients with severe chronic kidney disease, high ANGPTL2 circulating levels measured after kidney transplantation were associated with high serum endothelin-1 levels." (PMID 29138671, 2017). "It is not unlikely that similarly to how ANGPTL2 and TGFβ1 positively increase the expression of each other in chronic kidney disease, ANGPTL4 and TGFβ1 employ such reciprocal effects on each other expression." (PMID 29100268, 2017).
rheumatoid arthritis (6 papers, 2013 to 2026). A chronic, systemic autoimmune disorder characterized by inflammation in the synovial membranes and articular surfaces. "ANGPTL2 expression has recently been associated with rheumatoid arthritis, dermatomyositis, cancer, abdominal aortic aneurysms, and CAD." (PMID 26397985, 2015). "ANGPTL2 was able, in fact, to induce the chemotactic activity of rheumatoid arthritis synovial fluid-derived monocytes/macrophages and endothelial cells, promoting synovial inflammation." (PMID 29389861, 2018). "In rheumatoid arthritis patients, the ANGPTL2 concentration is increased (to about 25 ng/ml) in synovial fluid and the synovium." (PMID 28934245, 2017). "Schematic diagram of the mechanism of ANGPTL2 in the treatment of rheumatoid arthritis." (PMID 41820289, 2026). "Likewise in rheumatoid arthritis, high expression of ANGPTL2 has reported also in dermatomyositis." (PMID 29389861, 2018). "ANGPTL2 acts as an important rheumatoid synovium-derived inflammatory mediator in rheumatoid arthritis (RA) pathogenesis." (PMID 29389861, 2018). "Recently, we reported that ANGPTL2 functions as a chronic inflammatory mediator in obesity, atherosclerotic disease, rheumatoid arthritis (RA), and cancer." (PMID 23469106, 2013).
Stroke (6 papers, 2014 to 2024). Sudden impairment of blood flow to a part of the brain due to occlusion or rupture of an artery to the brain. "More recently, beneficial angiogenic properties of ANGPTL2 were reported in the context of stroke and one study demonstrated that ANGPTL2 displays antithrombotic properties." (PMID 29138671, 2017). "Furthermore, relevant to clinical application, attenuation of acute brain inflammation seen in the “penumbra” of Angptl2 KO mice could be useful, as protecting the “penumbra” in stroke patients is the main purpose of therapy against acute brain infarction." (PMID 27861531, 2016).
skin squamous cell carcinoma (5 papers, 2015 to 2023). A carcinoma arising from the squamous cells of the epidermis. "ANGPTL2 has also been reported to promote lymph node and distant metastases in skin squamous cell carcinoma through tumour angiogenesis." (PMID 37386055, 2023). "ANGPTL2 expression has been correlated with the frequency of carcinogenesis in chemically-induced skin squamous-cell carcinoma of mice." (PMID 31384179, 2019). "In a chemically induced skin squamous cell carcinoma model, transgenic mice constitutively expressing ANGPTL2 under the keratinocyte-specific promoter K14 exhibited accelerated skin carcinogenesis, more mesenchymal tumors, and increased metastases." (PMID 25360865, 2015). "ANGPTL2 was found to increase inflammatory carcinogenesis in a chemically induced skin squamous cell carcinoma." (PMID 25370833, 2015). "Increasing expression levels of ANGPTL2 were measured during carcinogenesis in a chemically induced skin squamous cell carcinoma model." (PMID 25360865, 2015). "Moreover, ANGPTL2 promotes EMT via activating TGF-β-Smad pathway in a mouse model of skin squamous cell carcinoma (SCC) expressing ANGPTL2." (PMID 29389861, 2018).
colon cancer (4 papers, 2017 to 2024). "We recently demonstrated that cancer-associated fibroblast (CAF)-derived ANGPTL2 exhibits anti-tumor activities in an AOM/DSS mouse model of colitis-associated colon cancer, in a mouse kidney cancer model, and in murine syngeneic tumor models." (PMID 37736764, 2023). "Furthermore, we reported that ANGPTL2 activates NFATc3 in colon cancer cells." (PMID 37452654, 2023). "Another study demonstrated that low expression of miR-204 correlates to colon cancer pathogenesis, CRC progression, and drug resistance through overexpression of angiopoietin-like protein 2 (ANGPTL2)." (PMID 38632250, 2024). "Our study shows that glucocorticoids reduced prostanoids, urokinase-type plasminogen activator (uPA) and angiopoietin-like protein-2 (ANGPTL2) levels, but increased angiogenin (ANG) in supernatant from human CT5.3hTERT colon cancer-derived myofibroblasts." (PMID 27717848, 2017).
liver cancer (4 papers, 2018 to 2021). An epithelial or non-epithelial malignant neoplasm that arises from the liver. "In addition, a study demonstrated that miR-221 bound directly to the 3’-untranslated region of Angptl2 and inhibited the expression of Angptl2 in liver cancer cells, thus decreasing cell proliferation, clonogenicity, and migration/invasion." (PMID 34638684, 2021). "Numerous glycoproteins have been confirmed to screen AFP-negative liver cancer in clinical studies, including Golgi protein 73 (GP73), dickkopf-1 (DKK1), angiopoietin-like protein 2 (ANGPTL2), and haptoglobin (Hp)." (PMID 33889548, 2021).
periodontitis (4 papers, 2017 to 2026). An acute or chronic inflammatory process that affects the tissues that surround and support the teeth. "Previous studies have demonstrated that ANGPTL2 deficiency aggravates alveolar bone loss in periodontitis, a condition that shares mechanistic similarities with RA in terms of bone destruction." (PMID 41820289, 2026). "Background/Objectives: Recent studies suggest that angiopoietin-like protein 2 (ANGPTL2) is one of the factors contributing to disease progression in distant organs associated with periodontitis." (PMID 41899283, 2026). "ANGPTL2 expression was markedly elevated in periodontal tissues, serum, and colorectal tumors in the periodontitis group." (PMID 41899283, 2026). "Elevated ANGPTL2 concentrations are present in gingival crevicular fluid (GCF) from chronic periodontitis patients and stimulation with P. gingivalis LPS up-regulated ANGPTL2 mRNA and protein levels in gingival squamous cell carcinoma Ca9-22 cells." (PMID 30837987, 2019). "Via this pathway, ANGPTL2 functions in the pathogenesis of periodontitis and contributes to prolonging chronic inflammation in patients with systemic disease." (PMID 28934245, 2017). "Since P. gingivalis is one of the most important periodontal pathogens, it is possible that ANGPTL2 is produced from gingival epithelial cells during periodontitis progression." (PMID 28934245, 2017). "We demonstrated an increased ANGPTL2 concentration in gingival crevicular fluid from chronic periodontitis patients." (PMID 28934245, 2017). "We found increased ANGPTL2 concentrations in gingival crevicular fluid (GCF) samples from chronic periodontitis (CP) patients." (PMID 28934245, 2017). "Given the established link between periodontitis and RA, these findings suggest that ANGPTL2 may also play a protective role in RA-related joint pathology." (PMID 41820289, 2026). "We previously reported that periodontitis promotes hepatocellular carcinoma and that ANGPTL2 may be involved in tumor progression." (PMID 41899283, 2026). "Thus ANGPTL2 participates in the pathogenesis of periodontitis and may promote continuous chronic inflammation." (PMID 30837987, 2019).